IGHV1-24 (immunoglobulin heavy variable 1-24)
Description:
V region of the variable domain of immunoglobulin heavy chains that participates in the antigen recognition. Immunoglobulins, also known as antibodies, are membrane-bound or secreted glycoproteins produced by B lymphocytes. In the recognition phase of humoral immunity, the membrane-bound immunoglobulins serve as receptors which, upon binding of a specific antigen, trigger the clonal expansion and differentiation of B lymphocytes into immunoglobulins-secreting plasma cells. Secreted immunoglobulins mediate the effector phase of humoral immunity, which results in the elimination of bound antigens. The antigen binding site is formed by the variable domain of one heavy chain, together with that of its associated light chain. Thus, each immunoglobulin has two antigen binding sites with remarkable affinity for a particular antigen. The variable domains are assembled by a process called V-(D)-J rearrangement and can then be subjected to somatic hypermutations which, after exposure to antigen and selection, allow affinity maturation for a particular antigen.
Synonyms: IGHV124; VH
Gene: Immunoglobulin variable (V) gene on chromosome 14 (106,276,548 to 106,277,043, reverse strand). Ensembl gene ENSG00000211950.
Subcellular location: Secreted; Cell membrane
Gene Ontology:
Molecular function: antigen binding
Biological process: immunoglobulin mediated immune response
Cellular component: extracellular region; plasma membrane
Homologues: Orthologues: chimpanzee IGHV1-24 (80% identical), mouse Ighv1-50 (65% identical), mouse Ighv1-74 (65% identical), mouse Ighv1-69 (63% identical), mouse Ighv1-52 (62% identical), mouse Ighv1-53 (62% identical), mouse Ighv1-64 (62% identical), mouse Ighv14-1 (62% identical), mouse Ighv14-2 (62% identical), mouse Ighv1-55 (62% identical), mouse Ighv1-59 (62% identical), mouse Ighv1-61 (62% identical), and 48 more. Paralogues in human: IGHV1-69-2 (88% identical), IGHV1-2 (80% identical), IGHV1-3 (79% identical), IGHV1OR15-1 (79% identical), IGHV1-18 (78% identical), IGHV1-46 (78% identical), IGHV1-69 (75% identical), IGHV1-69D (75% identical), IGHV1-45 (73% identical), IGHV1OR21-1 (73% identical), IGHV1OR15-9 (72% identical), IGHV1-58 (71% identical), and 65 more.